INS (insulin)
Diseases named in the same sentence as INS in open-access papers (continued):
Sharing a sentence is not in itself a finding about the gene and the disease.
diabetes (continued). "A diagnosis of diabetes in a stroke patient would not only probably change the clinical management of that patient, specifically with respect to lipid and blood pressure management but also lead to possible institution of insulin administration." (PMID 25379056, 2014). "The case group had a higher prevalence of diabetes (37.8% vs. 9.5%, p<0.001), prevalence of diabetes treatment (insulin) (17.8% vs. 2.4%, p<0.001), prevalence of alcohol abuse (33.3% vs. 13.5%, p = 0.001), and proportion of patients with a BMI≥28 kg/m2 (57.8% vs. 36.1%, p<0.001)." (PMID 24748009, 2014). "Here, we found that rs16835198 was significantly associated with the levels of fasting insulin in normal weight subjects without diabetes, and that the presence of the major allele G had an insulin-desensitizing effect on these individuals." (PMID 25369206, 2014). "Type 2 diabetes mellitus (T2DM) patients have defects in insulin secretion." (PMID 25186493, 2014). "Thus, a P2Y6R agonist would be expected to produce beneficial effects for diabetes both with respect to insulin release from the pancreas and glucose homeostasis in certain insulin target tissues." (PMID 25549240, 2014). "In summary, the relevance of dysfunctional glucagon secretion to the pathogenesis of diabetes has been widely recognized and, for that reason, targeting glucagon and not only insulin secretion abnormalities in the treatment of T2D has gained increased interest." (PMID 25177371, 2014). "Using a quantitative systems pharmacology modeling approach, we combined ex vivo data of IL-1β effects on β-cell function and turnover with a disease progression model of the long-term interactions between insulin, glucose, and β-cell mass in type 2 diabetes mellitus." (PMID 24918743, 2014). "These alterations began early, after 15 days of diabetes induction, associated with a severe mitochondrial damage, and were not prevented by conventional insulin treatment." (PMID 24387617, 2014). "Serum B12 was measured using chemiluminescence immunoassay in 103 (43 male, 60 female) obese (mean body mass index (BMI) z-score ± SD (2.36 ± 0.29)), adolescents aged 10 to 17 years, median (range) insulin sensitivity index of 1.27 (0.27 to 3.38) and 13.6% had pre-diabetes." (PMID 25486369, 2014). "For example, 56% of the students falsely believed that all individuals with diabetes must take insulin injections, 55.4% falsely believed that individuals with diabetes can only eat special kinds of sweets, and 57% falsely identified liposuction as the best possible treatment for adiposity." (PMID 25360161, 2014). "In both insulin-dependent (Type 1) and noninsulin-dependent (Type 2) diabetics, abnormally high blood glucose is linked to nonphysiologic variations in plasma insulin content throughout a 24-hour period, sometimes too little, and at other times too much." (PMID 24782919, 2014). "Among those with diabetes, 92% had type 2 diabetes, and 24% were treated with insulin." (PMID 25237398, 2014). "Previous research showed that cancer patients with diabetes may have increased tumor cell proliferation and metastatic capacity as a consequence of the high insulin or increased free insulin-like growth factor (IGF-1) levels in hyperinsulinemic states." (PMID 25350747, 2014). "Therefore, in addition to basic knowledge of diabetes which should be transmitted at diagnosis, insulin requiring patients with diabetes demand regular and systematic education throughout their lives." (PMID 24397956, 2014). "Our findings demonstrating these effects of metformin in a rat insulinoma cell line have a great importance since β-cell protection and maintenance of insulin sensitivity in the β-cells are of particular significance in the prevention and treatment of diabetes." (PMID 24896641, 2014). "Furthermore, the lin28/let 7 pathway acts as a central regulator of mammalian glucose metabolism and insulin signaling therefore implicating this pathway in diabetes mellitus." (PMID 25594065, 2014).
diabetes (continued). "Long-acting insulin, such as insulin glargine, is suitable as a basal insulin therapy in diabetes." (PMID 25187822, 2014). "The findings of the present study indicate that a simultaneous administration of Nicotinamide and Streptozocin resulted in type 2 diabetes mellitus, characterized by increased blood glucose, lipid profile, and oxidative stress as well as with decreased serum insulin." (PMID 24644382, 2014). "Type-1 diabetes mellitus, in which insulin is absent, is associated with a collapse of spermatogenesis and increased germ cell apoptosis." (PMID 24885899, 2014). "However, the roles of free radicals on the effects of insulin that result in protection against cerebral ischemic insult in diabetes remain undefined." (PMID 25223305, 2014). "For example, SixUntilMe (named after the age at which the author, Kerri Morrone Sparling, was diagnosed with diabetes) features the life of a patient living with type 1 diabetes, discussing topics like insulin pumps, continuous glucose monitors, and diabetes advocacy." (PMID 24518354, 2014). "Taken together, these findings indicate that diabetes could promote tau phosphorylation via impaired insulin signaling in the brain and then, contribute to cognitive impairment." (PMID 25250014, 2014). "Moreover, the anti-aggregating effect of insulin is lost on patients with insulin resistance as it can occur in obesity, diabetes mellitus, arterial hypertension, or in MS." (PMID 25243022, 2014). "Diabetes is significantly associated with a higher risk of lung cancer, but insulin use does not increase the risk." (PMID 24991802, 2014). "Hence, the importance of further studies with acute and chronic exercise protocols in obese and obese with diabetes population is clear, particularly to understand better the effects of physical exercise on insulin signaling pathway." (PMID 24728251, 2014). "Diabetes mellitus is described as a disease syndrome with a collection of metabolic disorders characterized by chronic hyperglycemia which results from defects in insulin secretion, insulin action, or both." (PMID 25358757, 2014). "Diabetes is one of the most common chronic diseases characterized by hyperglycemia as a result of impaired insulin secretion by pancreatic β cells and by cellular resistance to insulin." (PMID 24688431, 2014). "This diabetes-induced renal oxidative stress was prevented by insulin treatment." (PMID 25243053, 2014). "A significantly earlier requirement of insulin therapy was observed in patients with thyroid disease onset prior to (group 1; 2.5 yrs; Q1 = 0.0, Q3 = 8.25) or within the same year (group 2; 0.0 yrs; Q1 = 0.0, Q3 = 0.75) of diabetes mellitus onset." (PMID 24580798, 2014). "Functional defects in the pancreatic beta-cell result in type 2 diabetes mellitus, a metabolic disorder in which, for various reasons, beta-cell insulin secretion may be profoundly affected at the multiple stages of the natural history of the disease." (PMID 25628604, 2014). "Because the pathophysiologic nature of type 2 diabetes (T2D) is characterized by progressive decline in insulin secretion, the aim was to determine whether GA levels were affected by diabetes duration in subjects with T2D." (PMID 25265016, 2014). "Diabetes mellitus is a condition characterized by a high blood glucose level occurring from inability of the pancreas to produce enough insulin or cells stop responding to the insulin that is produced." (PMID 25152815, 2014). "Diabetes comprises a group of metabolic disorders characterised by chronic hyperglycaemia with disorders in the metabolism of carbohydrate, fat, and protein that result in defects in secretion and action of insulin." (PMID 25574393, 2014). "These evidences further support the idea that impaired insulin function and signaling may constitute another common mechanistic link between diabetes (particularly T2D) and AD." (PMID 25071725, 2014).
diabetes (continued). "Conversely patients with diabetes receiving insulin had a ~2-3 fold increased risk of mortality compared to patients with no diabetes." (PMID 25361884, 2014). "However, in patients with diabetes, this regulation is compromised due to either a dysfunction of insulin secretion or sensitivity or occasionally both." (PMID 25435876, 2014). "In insulin-dependent patients, duration and level of diabetes control (HbA1c > 7) were higher." (PMID 24495383, 2014). "In light of the increased incidence of diabetes in the young population, future focus on the correlation between insulin dysfunction and Tau pathology may provide invaluable information for the treatment and prevention of sporadic AD." (PMID 24574966, 2014). "While the chronic use of vitamin C may not be a definitive solution, the evidence that the MedDiet improves GLP-1 action on both insulin secretion and endothelial dysfunction in diabetes might shed new light on the daily management of this disease." (PMID 25407792, 2014). "It has also been reported that Cd might down-regulate glucose transporter-4 (GLUT4) translocation by insulin and enhanced the induction of pancreatic beta cells’ disruption in diabetes." (PMID 24401367, 2014). "Further, regulation of miR-196b expression by glucose suggests an additional level of regulation of insulin biosynthesis by a novel mechanism that could play an important role in the case of diabetes." (PMID 25003985, 2014). "We did additional sensitivity analyses by adjusting with three different Cox models: 1) controlling for gender and quartiles of age as strata; 2) also controlling for the diabetes parameters duration and HbA1c; 3) additionally controlling also for insulin treatment." (PMID 25198347, 2014). "Additionally, decreased expression of skeletal muscle GLUT 4 in diabetes resulted in the reduction of insulin-mediated glucose uptake into skeletal muscle." (PMID 24417880, 2014). "Our data may have relevance in improving appropriate prescription drug use of best practice in patients affected by other neuromuscular disorders and diabetes or insulin/glucose dismetabolism." (PMID 25505577, 2014). "This metabolic stress may exhaust β-cells, leading to insulin secretion dysfunction and the development of diabetes mellitus later in life." (PMID 25105792, 2014). "In both studies insulin-treated patients with diabetes had the poorest 10-year survival rate." (PMID 24447406, 2014). "The empirical algorithm based on age at diabetes onset and early initiation of insulin therapy may exclude younger-onset T2DM patients and include older-onset T1DM patients." (PMID 24990184, 2014). "This is a particular issue in children with diabetes, among whom subcutaneous insulin injections may be inadvertently delivered to muscle tissue, leading to altered insulin absorption and increased risk of hypoglycaemia." (PMID 24466182, 2014). "Mice lacking survivin in β-cells develop insulin-deficient diabetes after birth due to a failure of β-cell mass expansion and show defective β-cell mass expansion and proliferation after pancreatic injury." (PMID 24695557, 2014). "These target miRNAs are closely associated with dysregulation of insulin/PI3K-AKT signaling, suggesting that the Cmah-null mice could be a useful model for studying diabetes." (PMID 25243123, 2014). "Finally, we were able to examine providers’ familiarity with currently available diabetes treatments such as early initiation of insulin therapy and implementation of multifactorial interventions that remain relevant to modern practice and guidelines." (PMID 25199672, 2014). "There are many probable mechanisms for this; zinc is important with regard to metabolic diseases such as insulin resistance, metabolic syndrome (MS) and diabetes mainly because it is required for insulin storage in the pancreas and stabilization of insulin hexamers." (PMID 24416185, 2014).
diabetes (continued). "Because blood glucose is typically used as the diagnostic marker of diabetes mellitus, but not insulin, many of these individuals remain undiagnosed." (PMID 24949486, 2014). "Therefore, we can conclude that D#22 cells are potentially a more useful cell source for β-cell replacement therapy in diabetes than iPS cells because the former are safer and capable of generating greater numbers of functional insulin-producing cells." (PMID 24886514, 2014). "In our studies, pathway analysis indicated miRNAs mentioned previously might be involved in the insulin signaling pathway and type 2 diabetes mellitus." (PMID 24983625, 2014). "Insulin therapy is a common practice for treating type 2 diabetes mellitus." (PMID 24949486, 2014). "However, in hungry or diabetes mellitus patients, blood ketone bodies level are greatly increased due to low insulin and high fatty acid levels, and they becomes the major energy supplier of the myocardium." (PMID 24505394, 2014). "In our laboratory, we hypothesized that glucoregulatory hormones such as glucagon and somatostatin, in addition to insulin, are relevant for embryo-fetal development and diabetes-derived alterations." (PMID 24977161, 2014). "Diabetes mellitus represents a group of complex metabolic diseases that result in impaired glucose homeostasis, which includes destruction of β-cells or the failure of these insulin-secreting cells to compensate for increased metabolic demand." (PMID 25071830, 2014). "The actual Cochrane report regarding “Insulin and oral agents for managing cystic fibrosis-related diabetes” stated that further studies are needed to establish whether there is clear benefit for hypoglycemic agents." (PMID 24620855, 2014). "We showed that insulin treatment delayed fiber loss in the short term diabetes but was not able to prevent it in long term." (PMID 24387617, 2014). "In conclusion, CMHX008 shared the comparable insulin-sensitizing effects as rosiglitazone with lower adipogenic capacity and might potentially be developed into an effective agent for the treatment of diabetes and metabolic disorders." (PMID 25004107, 2014). "Age at diabetes onset correlated with insulin-free period (p < 0.001)." (PMID 24580798, 2014). "In addition, IL-10 over-expression can inhibit IL-1β-induced Fas expression and apoptosis of insulin secreting cells, reduce the incidence of diabetes of prediabetic NOD mice, and delay or even prevent T1D development." (PMID 24663217, 2014). "Diabetes mellitus (DM) is a heterogeneous group of metabolic disorders characterized by hyperglycemia with impaired metabolism of carbohydrate, fat, and proteins as a result of defects in insulin secretion, insulin action, or both." (PMID 24936198, 2014). "Interestingly, the clinical insulin modulator and diabetes drug, metformin and the serotonin modulator Fluoxetine/Prozac that is used in depression treatment, each alter chemotherapy sensitivity in cancer cells." (PMID 24885890, 2014). "To overcome this, we used Akita mice, which are a non-obese, insulin-deficient diabetes model with no insulin resistance." (PMID 24743240, 2014). "Irrespective of these changes, deletion of receptors for either incretin hormone did not greatly affect the course of severe insulin deficient diabetes." (PMID 24967820, 2014). "Of these 287 individuals with NGT who had measures of carbohydrate oxidation rate during insulin stimulation at baseline (baseline age 26.4 ± 6.0 years) and also had follow-up data for development of diabetes (follow-up time 7.8 ± 8.2 years), 99 (34%) developed type 2 diabetes." (PMID 24728127, 2014). "Women with glucose intolerance or diabetes postpartum also had a significant impaired beta-cell function and lower insulin sensitivity, remaining significant after adjustment for age, BMI, ethnicity, breastfeeding, contraception, multiparity, and corticoid treatment." (PMID 25180037, 2014).
diabetes (continued). "The Diabetes Control and Complications Trial (DCCT) demonstrated the long-term benefits of intensive insulin treatment; however, the increased risk of hypoglycaemia and increased staff resources used in the DCCT have perhaps limited the adoption of this approach even more widely." (PMID 24511312, 2014). "These quantitative studies will help build better models to describe glucose-induced Ca2+ oscillations in diabetic beta-cells, which will provide insights into the development of insulin secretion dysfunction and beta-cell failure in the development of diabetes." (PMID 25053525, 2014). "Insulin is a polypeptide hormone required to be taken in patients suffering from diabetes mellitus." (PMID 26556194, 2014). "Our results have shown increase in placental weight in both the groups but a significant increase in placental weight is observed when glycemic control was done with diet control plus injectable insulin as compared to diabetics controlled on diet and exercise only." (PMID 24772119, 2014). "This is because intensive insulin therapy not only controls elevated glucose levels in the critically ill, but has been shown to significantly improve outcomes among hospital in patients with acute hyperglycaemia or newly diagnosed diabetes." (PMID 25379056, 2014). "The clinical phenotype of the GCK-PNDM individuals in our case series is similar to that observed in the literature to date: very low birth weight, typically <2.5th centile; diagnosis of diabetes within the first few months of life; and insulin treatment required." (PMID 25015100, 2014). "Thus, advanced age at diabetes onset in our groups 1 and 2 can partially be attributable for their earlier insulin requirement." (PMID 24580798, 2014). "Further research is needed to examine whether and how insulin pumps may deliver on their promise of improved diabetes control for people with type 1 diabetes." (PMID 24884679, 2014). "Rhythmic control of insulin release is deregulated in humans with diabetes." (PMID 25414671, 2014). "In addition, post-load glucose of incident diabetes cases showed a rapid increase 5 years before diagnosis, which is followed by a rapid decrease in insulin sensitivity." (PMID 25167060, 2014). "“Negative feelings about total life with diabetes” was significantly associated with interdependence, perceived emotional support, self-esteem, sex, oral hypoglycemic agent, insulin and complications." (PMID 25333692, 2014). "Metformin, an insulin-sensitizer, may correct several physiologic abnormalities owing to insulin resistance in patients with type 2 diabetes mellitus (DM)." (PMID 25510597, 2014). "Because we excluded those who received any insulin during the prior six months, our cohort, while focusing on poorly-controlled diabetes, may have tended to exclude those with particularly labile glycemic control." (PMID 25339147, 2014). "Based on the results of glucose and GIR, week 10 (rats fed with high-fat diet for 10 weeks) and week 15 (rats fed with high-fat diet plus low-dose STZ intraperitoneal injection) were considered as different stages of T2DM pathogenesis, that is insulin resistance and overt diabetes." (PMID 25177707, 2014). "The decreased levels of liver ENPP1 during hyperglycaemic conditions such as diabetes may be a compensatory response to increase insulin signalling and regain control of glucose homeostasis." (PMID 25539584, 2014). "Diabetes also compromises glucose metabolism, insulin signaling, and mitochondrial function." (PMID 25250014, 2014). "We excluded participants receiving insulin; 74% were taking oral diabetes medications." (PMID 24717684, 2014). "It is premature to consider kisspeptin-54 as a therapeutic for HA; however, one potential advantage of administering kisspeptin-54 over GnRH would be its suitability for constant pump administration, which is increasingly used to deliver insulin therapy to certain patients with diabetes." (PMID 24517142, 2014).